AQP4 (aquaporin 4)
Diseases named in the same sentence as AQP4 in open-access papers (continued):
Sharing a sentence is not in itself a finding about the gene and the disease.
diabetes (30 papers, 2010 to 2025). "The frequency of the cardiovascular risk factors diabetes and hypertension was similar in AQP4-IgG+NMOSD and MOGAD, while smoking was more prevalent in MOGAD." (PMID 40693183, 2025). "Vascular risk factors, including diabetes, dilate the perivascular space, disrupting the glymphatic system and the active regulation of AQP-4." (PMID 39201439, 2024). "AQP4 expression was found to be significantly increased in the rat retina during diabetes, especially in RMCs." (PMID 36531955, 2022). "Retinal cystoid edema indicates the drainage dysfunction of RMG due to the misdistribution and decreased expression levels of ion and water channels, including inwardly rectifying K+ channel 4.1 (Kir4.1) and aquaporin 4 (AQP4), affected by diabetes." (PMID 35002773, 2021). "Twelve AQP4-ab-positive NMOSD patients were excluded due to diabetes mellitus (n = 3), arterial hypertension (n = 2), and concomitant autoimmune conditions (n = 7)." (PMID 33717149, 2021). "Diabetes is known to enhance the amount of retinal expression of AQP4 and down-regulation of AQP4 exacerbated experimental DR through increased expression of pro-inflammatory factors." (PMID 29565290, 2018). "Increased AQP4 expression has been observed in animal models of induced diabetes, and AQP4 knockdown in diabetic animals led to aggravation of retinopathy." (PMID 27571065, 2016). "In contrast, modulation of retinal AQP1 and AQP4 expressions was observed during experimental diabetes; AQP1 expression was induced on glial cells and in the innermost retinal layers." (PMID 20383338, 2010). "There was no statistical difference involving the EG and the CG in terms of age, gender, BMI, course of disease, EDSS score, AQP4-IgG positivity, annual recurrence rate, hypertension, and diabetes (P > 0.05), indicating that the two groups were well comparable." (PMID 41267969, 2025). "Our data showed that the retinal protein expression levels of Kir4.1, AQP4 and Dp71 were decreased with diabetes progression and the distributions of these proteins were also changed, causing the dysfunction of Müller cells with intracellular edema in experimental DR." (PMID 33865457, 2021). "The role of AQP-4 and Kir4.1 in the regulation of water transport and edema formation has been well-described in retinal ischemia-reperfusion, ocular inflammation, retinal detachment and diabetes." (PMID 33661927, 2021). "Normally, Kir4.1 and AQP4 are overlapped in space and concentrated in the end-feet and perivascular processes of Müller cells, although this polarized expression of Kir4.1 is strongly reduced in experimental diabetes." (PMID 33523201, 2021). "Furthermore, diabetes-mediated downregulation of Kir4.1 and upregulation of AQP4 was partially reversed by pinacidil." (PMID 33523201, 2021). "There were significant differences in the levels of hypertension (5.56% vs. 18.18%; p = 0.042), diabetes (0.00% vs. 12.73%, p = 0.007), anti-AQP-4 antibodies (31.8% vs. 58.18%, p = 0.009), and the relapse rate (31.48% vs. 67.27%, p < 0.001) between these two groups." (PMID 31852443, 2019). "Therefore, AQP4 is considered an early marker of RMCs alterations in diabetes." (PMID 36531955, 2022). "In AQP4‐NMOSD, the two most common CVC/RF comorbidities included hypertension (n = 29) and diabetes mellitus (n = 12), followed by dyslipidemia (n = 11)." (PMID 40485599, 2025). "AQP4 levels in the aqueous humor were also significantly elevated in patients with diabetes (including those without clinical features of retinopathy)." (PMID 36531955, 2022). "In particular, GFAP and AQP4 levels were higher also in diabetic eyes without clinical signs of DR, and they have been suggested as early biomarkers of diabetes-induced retinal stress." (PMID 34216255, 2021). "Of interest, is the upregulation of one of the genes, aquaporin 4, (AQP4, 2.24) due to diabetes." (PMID 23028588, 2012).
diabetes (continued). "Thus, certain comorbidities, such as diabetes or orthopedic conditions, could independently influence OCT or EDSS findings, respectively, regardless of AQP4‐NMOSD/MOGAD disease activity." (PMID 40485599, 2025).
encephalomyelitis (30 papers, 2016 to 2026). Inflammation of the brain and the spinal cord. "NMOSD is an idiopathic inflammatory central nervous system disease characterized by the presence of AQP4 antibodies." (PMID 41267969, 2025). "Astrocyte loss resulted in the worsening of symptoms in a stage-dependent manner in Theiler`s murine encephalomyelitis, together with dysregulation of Aquaporin-4 (AQP4)." (PMID 38213874, 2024). "In direct comparison, IHC titres were higher on average than those in the majority of patients with AQP4-IgG-positive NMOSD or MOG-IgG-positive encephalomyelitis tested by the authors in recent years using the same methodology." (PMID 27776522, 2016). "Missing OCB or granulocytic pleocytosis should thus prompt physicians to challenge the diagnosis in patients with suspected MS and to consider MOG-IgG- or AQP4-IgG-positive encephalomyelitis." (PMID 27793206, 2016). "However, we provide evidence that an AQP4-specific T cell response evoked from a natural polyclonal T cell repertoire is able to induce encephalomyelitis at sites that recapitulate the lesion localization in human NMOSD." (PMID 39934927, 2025). "In secondary lymphoid tissue, mature AQP4-specific T cells are not deleted by WT B cells that express AQP4 after immunization with full-length AQP4 but rather expand and induce encephalomyelitis." (PMID 38383779, 2024). "Yet, immunization of Treg‐cell depleted WT mice with AQP4 protein failed to induce clinical signs of encephalomyelitis." (PMID 28058717, 2017). "Both MOG-IgG-positive encephalomyelitis and AQP4-IgG-positive NMOSD are not usually found in a paraneoplastic context." (PMID 27802825, 2016). "As not all NMOSD patients develop anti-AQP4 Abs and false-positive results may be obtained in the case of other inflammatory diseases of the central nervous system (CNS), the diseases are often mistakenly diagnosed and improperly treated, resulting in a rapid accumulation of disability." (PMID 32244639, 2020).
intracerebral hemorrhage (29 papers, 2014 to 2025). A cerebrovascular disorder characterized by bleeding into one or both cerebral hemispheres including the basal ganglia and the cerebral cortex. "Increased AQP4 expression in intracerebral hemorrhage (ICH) rat models has been associated with enhanced brain tissue edema." (PMID 41270129, 2025). "The relationship between AQP4 and Aβ was analysed in a study published in March 2021, which focused on the circulating levels of AQP4 and the cerebral amyloid angiopathy-associated intracerebral haemorrhage (CAA-ICH)." (PMID 36115967, 2022). "Furthermore, immunohistochemical analysis and real-time quantitative polymerase chain reaction of AQP4 in rat brains showed an association between iron overload, AQP4 expression increase and intracerebral hemorrhage." (PMID 39194687, 2024). "Liu et al37 investigated the role of AQP4 in hematoma clearance following intracerebral hemorrhage in rat and murine models, respectively, under conditions of regulated AQP4 expression." (PMID 41050965, 2025). "In our previous paper, we investigated the localization of AQP4 by immunostaining in the hematoma-surrounding area of an intracerebral hemorrhage model." (PMID 38892076, 2024). "A recent work illustrates that the restoration of the Aqp4 expression in a murine model of intracerebral hemorrhage retrieves BBB integrity and inhibits BBB leakage." (PMID 37189354, 2023). "We are aware of only one study describing the levels of AQP4 in the blood in neurological disorders, suggesting the lower the serum AQP4 levels, the higher the number of cerebral microbleed evaluated by MRI in the patients with Intracerebral Hemorrhage." (PMID 35401278, 2022). "In intracerebral hemorrhage, AQP4 is involved in the protection of the BBB through a variety of mechanisms." (PMID 35111362, 2022). "AQP4 is abundantly expressed in astrocytes and is involved in the occurrence of brain edema following intracerebral hemorrhage." (PMID 32138732, 2020). "A similar involvement of AQP4 has also been documented in edema formation surrounding the clot in animal models of intracerebral hemorrhage with spontaneous and traumatic hematomas sharing main features of perifocal brain swelling." (PMID 30333785, 2018). "In murine intracerebral hemorrhage models, Cerebrolysin-treated animals exhibited significant reductions in IL-1β, IL-6, and TNF-α, as well as in aquaporin-4 (AQP4)—a main mediator of vasogenic edema." (PMID 40362194, 2025). "In mice with intracerebral hemorrhages, ADSC transplantations alleviates brain edema by inhibiting inflammation and Aquaporin 4 (AQP4) protein expression." (PMID 35454994, 2022). "Murine intracerebral hemorrhage models exposed to Cerebrolysin revealed significant reductions in pro-inflammatory markers such as IL-β, IL-6 and TNF-α as well as aquaporin-4, an important mediator for hematoma-induced vasogenic edema." (PMID 33143640, 2020). "We previously reported that aquaporin-4 deletion (AQP4−/−) in mice increased edema and altered blood-brain barrier integrity following intracerebral hemorrhage (ICH)." (PMID 25359421, 2014). "In mice with intracerebral hemorrhage, CURC dose-dependently decreased AQP4 and AQP9, but not AQP1 expression, through the NF-κB signaling pathway." (PMID 29292793, 2017).
Sjögren syndrome (28 papers, 2009 to 2025). "One patient of ours with AQP4-IgG positive NMOSD (case 1) also had a diagnosis of Sjögren Syndrome." (PMID 35054412, 2021). "The proportion of patients who were positive for concomitant rheumatological antibodies, especially the SSa/SSb and Ro52 for Sjogren's syndrome, was higher in the AQP4-ON group." (PMID 34272440, 2021). "Published experience of tocilizumab use in pediatric patients includes a 14-year-old boy suffering from NMOSD and Sjogren's syndrome and two female adolescents with AQP4 IgG positive NMOSD who relapsed during rituximab treatment." (PMID 32671002, 2020). "AQP4-seropositive NMO is frequently associated with these systemic autoimmune diseases, such as Sjögren’s syndrome and SLE." (PMID 23819854, 2013). "Additional antibodies detected in the patients' blood included anti-Yo antibody in the patient with prostate cancer (case 4) and anti-AQP4 antibody and anti-Ro/SSA antibody in the patient with NMO and Sjögren syndrome (case 5)." (PMID 34539561, 2021).
CNS demyelinating diseases (27 papers, 2011 to 2025). "Indeed, although NMO is a demyelinating disease of the CNS that shares several clinical features with MS, autoantibodies to aquaporin-4 are diagnostic of the disease and have been identified as a key pathogenic mediator of CNS damage, mechanistically setting it apart from MS." (PMID 35734473, 2022). "The serum was negative for antibodies associated with CNS demyelinating diseases, such as antibodies to aquaporin 4 (AQP-4), glial acidic fibrillary protein (GFAP), and myelin oligodendrocyte glycoprotein (MOG)." (PMID 38953026, 2024). "MOG-IgG is a biomarker for patients with CNS demyelinating diseases that have distinct demographic, serologic, clinical, and radiologic features from classical MS and from AQP4-IgG-mediated NMOSD, suggesting that MOG-IgG might mediate a distinct disease." (PMID 33281728, 2020). "Neuromyelitis optica (NMO) is another example of restricted lesion distribution in CNS demyelinating diseases, being originally characterized primarily by the presence of optic nerve and longitudinally extensive spinal cord lesions and the presence of aquaporin 4 (AQP4) autoantibodies." (PMID 28533776, 2017). "Therefore, we decided to investigate the frequency and titer levels of IgG antibodies to MOG and AQP4 in a multicenter study of patients with CNS demyelinating diseases using a live cell staining immunofluorescence assay with HEK-293A cells transfected with either AQP4 or MOG." (PMID 22204662, 2011). "The common atypical ON cases, characterized by biomarkers such as aquaporin-4 (AQP4) and myelin oligodendrocyte glycoprotein (MOG) antibodies, represents distinct CNS demyelinating diseases." (PMID 40606143, 2025). "With the discovery of AQP-4 IgG, the consensus regarding the pathogenesis of NMOSD has shifted from a strictly autoimmune condition to a CNS demyelination disease mediated primarily by humoral immunity." (PMID 31575949, 2019). "By comparing this clearly distinct cohort to AQP-4+ NMO as well as MS, we propose that MOG+ CNS demyelinating disease represents a distinct novel disease entity." (PMID 31870389, 2019). "Even when intravenously transferred to wildtype AQP4-expressing C57Bl/6 mice, these AQP4-reactive T cells did not develop clinically meaningful behavioral manifestations or histological evidence of CNS demyelinating disease beyond meningeal inflammation (data not shown)." (PMID 25990016, 2015). "In contrast, samples of patients with lower AQP4-IgG antibody titers and all investigated serum samples of AQP4-IgG negative CNS demyelinating diseases and controls were not able to activate the complement cascade on the surface of AQP4-expressing HEK-293A cells." (PMID 22204662, 2011).
Hypertension (27 papers, 2018 to 2025). The presence of chronic increased pressure in the systemic arterial system. "The mechanisms underlying such association might be complex: during brain aging, hypertension and the loss of AQP-4 water channels could impair the drainage of local interstitial fluid, and disrupt alpha-synuclein clearance, for which the perivascular spaces function as an important pathway." (PMID 32581771, 2020). "In hypertension, astrocytes are perturbed, leading to the penetration of leukocytes into the parenchyma as well as disrupted fluid homeostasis via aquaporin 4 channel dysfunction, leading to the formation of ePVS." (PMID 41075070, 2025). "Our results showed an increase of AQP4 in OZRs, similar to the results in the diet-induced obese rats, as well as in the animal model of hypertension." (PMID 32397542, 2020). "However, age, gender, hypertension, anti-AQP4 antibody status, blood monocytes, lymphocyte count, TC, TG, LDL, ESR, CRP, and lymphocyte to HDL ratio were not significantly correlated with the initial EDSS score." (PMID 34777231, 2021). "After MR imaging, we assessed whether the total expression and localisation pattern of aquaporin 4 (AQP4) was affected in hypertension." (PMID 32590994, 2020). "Several mechanisms have been reported to mediate the hypertension-caused BBB disruption, including enhanced transendothelial cell transport, structure change in TJ and altered distribution of glucose transporter-1, increased expression of AQP4 in the end feet of astrocytes, and the like." (PMID 31632292, 2019). "In parallel, hypertension also affects the glymphatic drainage system, mainly involving elements within the NGVU microenvironment (i.e., PVS and AQP4 water channels) which result in waste accumulation in the brain and neurotoxicity, further leading to VaP." (PMID 34452169, 2021). "Our results showed an increase of AQP4 in cerebral areas of DIO rats, similar to increases observed in animal models of hypertension." (PMID 32120798, 2020). "Immunofluorescence was performed in different eye structures to analyze the effects of hypertension in the expression of AQP1, AQP4, and the Na+/K+ ATPase α1 and α2 subunits." (PMID 30428541, 2018).
autoimmune encephalitis (24 papers, 2013 to 2026). Inflammation of the brain secondary to an immune response triggered by the body itself. "Antibody-mediated central nervous system (CNS) disorders including those associated with aquaporin-4 or myelin oligodendrocyte glycoprotein IgG and autoimmune encephalitis often affect women of childbearing age." (PMID 36601293, 2022). "Further autoimmune encephalitis panel testing for antibodies to anti-aquaporin 4 (AQP4), anti-myelin oligodendrocyte glycoprotein (MOG), anti-N-methyl-D-aspartate receptor (NMDAR), anti-LGI1, and anti-GABABR in the patient's CSF and serum were negative." (PMID 34160439, 2021). "Indeed, the worsening of experimental autoimmune encephalitis after intraperitoneal injection of anti-AQP4 Abs in animal was dependant on a previous BBB breakdown and the presence of inflammatory cytokines." (PMID 23710199, 2013). "Cell-based assays for anti-aquaporin-4, anti-myelin oligodendrocyte glycoprotein, autoimmune encephalitis panel, and vasculitis workup were all negative, except for CSF positivity for GFAP α antibody." (PMID 38699059, 2024). "AQP4 antibody testing was positive and CSF testing for other antibodies of autoimmune encephalitis was negative." (PMID 35645973, 2022). "The transfection cytology methods were used to detect autoimmune encephalitis antibodies (NMDAR, AMPAR1, AMPAR2, LGI1, CASPR2, GABABR, DPPX, IgLON5, GlyRα1, GABAARα1, GABAARβ3, mGluR1, mGluR5, D2R, Neurexin-3α, GAD65, KLHL11, gAChR, AQP4, MOG, GFAP) in CSF and serum." (PMID 40771880, 2025). "Aquaporin 4 (AQP4), myelin oligodendrocyte glycoprotein (MOG), myelin basic protein (MBP IgG), and autoimmune encephalitis-related antibodies were negative." (PMID 39911384, 2025). "Aquaporin-4 (AQP4) antibody, N-methyl-D-aspartate receptor (NMDAR) antibody and GFAP antibody were all positive, whereas the remaining autoimmune encephalitis antibody tests were negative." (PMID 39464885, 2024).